STAT3 (signal transducer and activator of transcription 3)
Diseases named in the same sentence as STAT3 in open-access papers (continued):
Sharing a sentence is not in itself a finding about the gene and the disease.
cancer (continued). "In contrast with STAT3 gene mutations, constitutive activation of STAT3 and/or STAT5 at the protein level has occurred in many human cancer cell lines and primary tumors." (PMID 24662938, 2014). "The binding of STAT3 was studied because deregulation of this TF is known to be an important discriminant between the two subtypes of cancer." (PMID 24650281, 2014). "Numerous in vitro and in vivo studies indicate that STAT3 promotes tumorigenesis of a variety of cancers, thus it is generally recognized as an oncogene." (PMID 24995503, 2014). "A constitutively active form of Stat3, Stat3C, can transform cultured mouse fibroblasts, pointing to an etiological role of Stat3 in cancer." (PMID 24670366, 2014). "Other platinum (IV) compounds, such as CPA-1, CPA-7 and platinum (IV) tetrachloride, also inhibit STAT3 DNA-binding, thereby suppressing cell growth and increasing apoptosis in several types of human cancer cells." (PMID 24743778, 2014). "Celecoxib significantly reduced the expression level of phosphorylated signal transducer and activator of transcription 3 (p-STAT3) and cancer stem-like cell abilities." (PMID 24945311, 2014). "Knockdown of MUC16 inhibits in vitro and in vivo proliferation of cancer cells MUC16-triggered activation of STAT3 via JAK2 results in increasing cancer cell proliferation." (PMID 24886523, 2014). "Previous studies have demonstrated that STAT3 is constitutively activated in a variety of cancer cell types, including leukemic cells." (PMID 25417721, 2014). "Constitutive activation of STAT3, which has been demonstrated in a broad spectrum of solid and hematological cancers, often correlates with an unfavorable prognosis in cancer patients." (PMID 24995504, 2014). "This cross-talk between STAT3 and redox pathways suggests that STAT3 plays a critical role in oxidative stress-mediated cancer therapy." (PMID 24662938, 2014). "Because STAT3 can also be phosphorylated by the IL-6 signaling cascade and because IL-6 is one of the most ubiquitously deregulated cytokines in cancer, it is a rational biological target for therapeutic investigations." (PMID 25268165, 2014). "Unsurprisingly, inhibition of STAT3 results in decreased proliferation and increased apoptosis in cancer cells." (PMID 24743778, 2014). "MiR-124b-3p belongs to the miR-124 family, and tni-miR-124b-3p is highly conserved with human miR-124 (100% identity to the mature sequence), which has been demonstrated to target Stat3 in different types of cancer." (PMID 24800866, 2014). "Promotion of invasion and metastasis: Previous studies have shown that STAT3 can promote invasiveness and the metastatic potential of cancer cells." (PMID 24995504, 2014). "The second aim was to elucidate the mechanism by which MDSCs increase STAT3 activation in cancer cells." (PMID 25075523, 2014). "With attention to these newly emerging areas, we will gain greater insight into the consequence of STAT3 activation in the biology of human cancers." (PMID 24762632, 2014). "The roles and significance of STAT3 in cancer biology have been extensively studied for more than a decade." (PMID 24995504, 2014). "As a novel finding, we found, GSNO also induced nitrosylation of STAT3, which is a known player in chemoresistance and cell proliferation in OvCa and in cancer in general." (PMID 24887420, 2014). "We also used these antibodies to examine Stat3 isoform expression in a variety of cells, in particular, to assess the contribution of Stat3β to overall pStat3 levels within normal and cancer cells." (PMID 25268166, 2014). "Activated STAT3 promotes angiogenesis, inflammation, proliferation and survival of cancer cells and is frequently detected in numerous human tumors." (PMID 24932134, 2014). "Apparently, miR-21 forms a critical component of STAT3-mediated regulatory circuits that link inflammation to cancer." (PMID 25539644, 2014).
cancer (continued). "For the first time, we show that cancer cell-produced PGE2 transcriptionally upregulates IDO expression through the EP4/STAT3 signaling pathway." (PMID 25060643, 2014). "Genetic/epigenetic alterations underlie aberrant STAT3 signaling in cancer and perturbation of positive or negative regulatory components in the JAK/STAT pathway that can cause a persistent STAT3 activation are often detected in different tumors." (PMID 24662939, 2014). "The relationship between IL-6 and IFN-γ is striking given the often distinct roles of STAT1 and STAT3 in inflammation and cancer." (PMID 24412616, 2014). "As shown by Iliopoulos and coworkers, STAT3 is not only a downstream output of the inflammatory regulatory signal, but is part of the positive feedback loop linking inflammation to cancer." (PMID 24499937, 2014). "Specifically, it targets tyrosine-phosphorylated STAT3 and consequently inhibits cancer cell proliferation and induces apoptosis via a mechanism involving ubiquitin-proteasome degradation." (PMID 25594014, 2014). "Recent studies have demonstrated that the interplay between miRNAs and STAT3 broadly exists in cancer development and progression." (PMID 25594054, 2014). "STAT3 has been shown to regulate the migration and invasiveness of cancer cells by transcriptionally up-regulating the expression of focal adhesion-associated proteins." (PMID 24995504, 2014). "Taken together, it is clear that the roles of STAT3 in cancer are multi-faceted and far more complicated than one appreciated previously." (PMID 24995504, 2014). "While there have been other reports of ubiquitin-mediated degradation of STAT3, this is the first report of tyrosine-phosphorylated STAT3 being regulated by this pathway in hypoxic cancer cells." (PMID 25594014, 2014). "Constitutively active STAT3 is found in many cancers, and STAT3 has been proved to be an essential component acting downstream of many other oncogenes." (PMID 24594072, 2014). "Resveratrol has been shown to retard the growth of various cancer cells through multiple cellular signaling pathways, including the Src-STAT3, NF-κB, Wnt and Hh signaling pathways." (PMID 25069516, 2014). "The activated STAT3 pathway is involved in cell proliferation of endometrial, bladder, colon and renal cancers." (PMID 24743778, 2014). "IL-6–activated STAT3 is crucial for survival of several types of cancer cell, including multiple myeloma, a plasmacytic B-cell malignancy." (PMID 25344679, 2014). "Our study also supports the accumulating clinical and pathological evidence on the role of STAT3 in the aggressiveness of various cancers." (PMID 25216522, 2014). "Because it is constitutively activated during disease progression and metastasis in a variety of cancers, STAT3 has promise as a drug target for cancer therapeutics." (PMID 24743778, 2014). "A few recent studies demonstrated other positive feedback loops that connect STAT3, gene regulation, metabolism, survival and proliferation in cancer cells." (PMID 24995504, 2014). "As a result, these prevent intracellular STAT3 phosphorylation and promote cell death in human cancer cell lines." (PMID 24743778, 2014). "TRiC therefore regulates both Stat3 protein levels and its function, making Stat3 modulation by manipulation of its interaction with TRiC a potential approach for the treatment of cancer and inflammatory diseases." (PMID 24756126, 2014). "Side populations with cancer stem-like cells (CSC)-like activity from MCF7 cells exhibit high STAT3 activity, which is required for maintenance of the CSC population and/or behaviour." (PMID 25266665, 2014). "The interaction between STAT3 and Ras signaling pathways suggests that the functional status of STAT3 affects responses of cancer to treatment with agents targeting these signaling pathways." (PMID 24662938, 2014).
cancer (continued). "Reduced SOCS3 expression has also been observed in a variety of inflammation-related human cancers and cancer cell lines and correlated with strong STAT3 activity in these cells." (PMID 24757565, 2014). "Cumulative evidence has established that STAT3 has a critical role in the development of multiple cancer types." (PMID 24743778, 2014). "Recent advances in cancer biology and drug discovery efforts have shed light on targeting STAT3 globally and/or specifically for cancer therapy." (PMID 24743778, 2014). "Identification of agents that target STAT3 molecule is likely to be of significance in cancer chemoprevention." (PMID 25296162, 2014). "The screen was performed with 44,000 genome-wide microarray of MCF7 cancer cells where STAT3 mRNA expression was increased by 3.62-fold in MCF7-HER2 cells compared with MCF7 wild-type." (PMID 24297508, 2014). "In one study, pyruvate kinase M2 (PKM2), a protein that is known to be essential for the Warburg effect and proliferation of cancer cells, was found to activate STAT3 via catalyzing its phosphorylation at Y705." (PMID 24995504, 2014). "Signal transducer and activator of transcription 3 (STAT3) plays critical roles in tumorigenesis and malignant evolution and has been intensively studied as a therapeutic target for cancer." (PMID 24662938, 2014). "The goal was to demonstrate that HER2-positive, ER-positive cancer cells were more sensitive to Herceptin treatment when also exposed to Stattic, due to the inhibition of STAT3." (PMID 24297508, 2014). "In fact, this new alliance between PI3K and STAT3 has recently been reported in rat nodose ganglion neurons and in some human cancer cell lines." (PMID 25259522, 2014). "Signal transducer and activator of transcription-3 (STAT3), an oncogenic transcription factor, is often constitutively active in human cancer cells." (PMID 25180593, 2014). "The S1P1 receptor is a transcriptional target for signal transducer and activator of transcription 3 (Stat3), whose persistent activation is critical for the growth and survival of a range of cancers." (PMID 24970218, 2014). "Recent in vitro and in vivo studies have revealed that several strategies to target STAT3 signaling have been proposed as cancer therapies." (PMID 25242136, 2014). "Overviews on the importance of STAT3 signaling and targeting it with potential therapies for cancer in general have been the subject of recent reviews." (PMID 24722453, 2014). "In fact, several drugs targeting this pathway are in development or used in the clinic for the treatment of cancer including neutralizing anti-IL-6 antibodies and small molecule or peptide inhibitors of STAT3 and/or JAK2." (PMID 24657910, 2014). "After activation via phosphorylation, STAT3 proteins in the cytoplasm dimerize and translocate to the nucleus where they regulate the expression of critical genes involved in cancer progression." (PMID 25266147, 2014). "Signal Transducer and Activator of Transcription-3 (STAT3) is constitutively activated in many cancers where it promotes growth, inflammation, angiogenesis and inhibits apoptosis." (PMID 24804649, 2014). "The identification of Cebpb, Fos and Stat3 as downstream targets (direct or indirect) of the FoxO factors during cancer cachexia is significant, as each of these transcription factors have been identified to regulate the muscle atrophy program." (PMID 25539728, 2014). "On the other hand, silencing STAT3 decreased the potential of cancer cells to resist anoikis and to migrate." (PMID 25216522, 2014).
cancer (continued). "Second, it has been shown that both un-phosphorylated STAT3 and STAT3-DN can interact with NFκB in the nucleus to drive the expression of multiple cancer-related genes, such as RANTES, IL-6, IL-8, MET and MRAS." (PMID 24995504, 2014). "The signal transducer and activator of transcription (STAT)-3 plays an indispensable role in the progression of a wide variety of cancers." (PMID 24722453, 2014). "Significantly, we found that glutamine regulates the activation of STAT3, a mediator of signaling pathways which regulates cancer hallmarks in invasive OVCA cells." (PMID 24799285, 2014). "These activities depended on the presence of phosphorylated STAT3 in the cancer stem cells and on the ability of these cells to activate STAT3 in the immune cells." (PMID 24728412, 2014). "STAT3, one of the seven members of the STAT transcription factor protein family, has been implicated as a potential target for cancer therapy." (PMID 24505404, 2014). "Previous extensive studies have demonstrated that inappropriate activation of STAT3 occurs at a high frequency in a wide variety of human cancers, including leukemia and lymphoma." (PMID 24520283, 2014). "Here we demonstrate Stat3, a transcription factor activated in up to 50% of cancers, binds TRiC/CCT chaperonin and that TRiC is required for Stat3 biosynthesis and activity in vitro and within cells." (PMID 24756126, 2014). "In human prostate tumor tissues, elevated cancer stem-like cell markers coincide with those cells exhibiting high STAT3 activity and low AR expression." (PMID 24722453, 2014). "An interesting interplay exists between Stat3 and NF-κb, both transcription factors being persistently activated in cancer and regulating a great number of genes important for cancer-promoting inflammation [reviewed in Ref." (PMID 24723924, 2014). "Similar to the SOCS proteins, many PTPs involved in the regulation of the JAK/STAT3 signaling are repressed or silenced in cancer cells." (PMID 24995504, 2014). "The phosphorylated STAT3 is constitutively activated or overexpressed in a variety of human cancers including brain tumors." (PMID 24945311, 2014). "Constitutive activation of JAK/Stat3 is a feature of cancer cells where its major function is to promote proliferation and survival." (PMID 25119572, 2014). "The key findings of this study are that STAT3 plays a very important role in anoikis resistance and inhibiting STAT3 induces anoikis in cancer cells in vitro and in vivo." (PMID 25216522, 2014). "Analysis of the pathological characteristics of the tumors from which these tissue microarrays were generated revealed that cancers displaying activation of both STAT3 and STAT5 were more likely to be more differentiated, low-grade tumors." (PMID 24762632, 2014). "Extensive efforts have been and are being actively invested in developing and testing STAT3-targeted therapy against a variety of human cancers." (PMID 24743777, 2014). "Abnormalities in the JAK/STAT3 pathway are critical in the oncogenesis of several types of cancer and are involved in the survival, proliferation and metastases of CaP." (PMID 24520293, 2014). "Because of the vast data implicating STAT3 activation in cancer pathogenesis, inhibition of the STAT3 signaling pathway has tremendous implications in the treatment as well as reversing the drug resistance seen in OvCa patients." (PMID 24887420, 2014). "Over-expression of STAT3 or treatment with IL-6 not only increased anoikis resistance, but also protected the cancer cells from PL-induced anoikis." (PMID 25216522, 2014). "Unlike inflammatory conditions with transient STAT3 activation, STAT3 is aberrantly and constitutively activated in many cancers, including hematolymphoid malignancies." (PMID 25472725, 2014). "Sorafenib has been proved to downregulate STAT3 pathway in several types of cancer, and similar results were also found in this study." (PMID 25333973, 2014).
cancer (continued). "In contrast with STAT1, STAT3 promotes survival, proliferation and motility of cancer cells, and induces immune tolerance." (PMID 25355139, 2014). "Despite the extensive literature on the effect of oncogenes upon GJIC, the effect of Stat3 upon GJIC in cancer cells is unclear." (PMID 24670366, 2014). "STAT3 is a well-known signaling hub to mediate various cancer-related cellular functions including cell cycle, anti-apoptosis, migration, invasion, and angiogenesis." (PMID 25359779, 2014). "A prominent Src effector is the Signal Transducer and Activator of Transcription-3 (Stat3), a key cytoplasmic signal transducer which is often overactive in cancer." (PMID 24670366, 2014). "Our previous reports have shown that our novel synthetic compound, HO-3867, works, at least in part, via inhibition of the STAT3 signaling pathway in various cancer cell lines even at very early time points." (PMID 25594014, 2014). "We identified that Gln withdrawal selectively reduces phosphorylated STAT3 expression in high‐invasive cancer cells." (PMID 24799285, 2014). "Signal Transducer and Activator of Transcription 3 (STAT3) is activated in a majority of cancers, and promotes tumorigenesis and even metastasis through transcriptional activation of its target genes." (PMID 24995503, 2014). "STAT3 and cancer stem cells: In recent years, accumulating evidence suggests that STAT3 carries a critical role in promoting the self-renewal of cancer stem cells." (PMID 24995504, 2014). "Certain studies have previously shown that activated STAT3 is overexpressed in cancer tissues and cell lines." (PMID 24520293, 2014). "We further demonstrate that Mo-MDSC in human PC promote cancer stemness in a STAT3-dependent manner." (PMID 24652403, 2014). "It is clear that the roles of STAT3 in cancer cells are substantially more complicated that it was appreciated previously." (PMID 24995504, 2014). "In many cancer cell types, STAT3 can transcriptionally increase the expression of various anti-apoptotic proteins involved in the intrinsic apoptotic pathway, such as survivin and the Bcl-2 family members (e.g., Bcl-xL, Bcl-2 and Mcl-1)." (PMID 24995504, 2014). "Together, STAT3 activation in both tumors and immune cells contributes to several malignant phenotypes of human cancers and to compromised anti-cancer immunity, together leading to poor clinical outcomes." (PMID 24743777, 2014). "Suppression of the STAT3 signaling pathway therefore represents a validated target for cancer therapy." (PMID 24932134, 2014). "The cells with activation of both STAT3 and STAT5 displayed changes in gene expression that paralleled the differences seen in the primary cancers displaying co-activation of STAT3 and STAT5." (PMID 24762632, 2014). "We believe our results are the first to show that Gln deprivation regulates the phosphorylation of STAT3, an oncogenic transcription factor, and thereby induces rewiring of cancer metabolic pathways." (PMID 24799285, 2014). "Accumulating data suggest that aberrant STAT signaling, and in particular STAT3 initiated cascades, participate in the development and progression of human cancers." (PMID 25344679, 2014). "Constitutive activation of STAT3 has been observed in prostate, pancreatic, pituitary gland, brain, ovarian and a number of other cancers." (PMID 25360166, 2014). "JAK2/STAT3 is one of the major signaling pathways triggered by IL-6 and is constitutively activated in numerous cancer cell lines and types, including GC tissues." (PMID 24527098, 2014). "For example, both paracrine and autocrine IL-6 signaling activates NF-κβ in cancer cells, and there is substantial crosstalk between NF-κβ and STAT3, leading to their positive or negative regulation." (PMID 24722453, 2014). "This, to our knowledge, is the first report of a correlation between Stat3β levels and levels of constitutive Stat3 phosphorylation in cancer cells." (PMID 25268166, 2014).